MIR8071-1 (microRNA 8071-1)
Synonyms: hsa-mir-8071-1
Gene: MicroRNA gene on chromosome 14 (105,621,116 to 105,621,180, forward strand). Ensembl gene ENSG00000274172.
Homologues: Paralogues in human: MIR8071-2 (100% identical).